HOXB1 (homeobox B1)
Diseases named in the same sentence as HOXB1 in open-access papers (continued):
Sharing a sentence is not in itself a finding about the gene and the disease.
atrioventricular septal defects (1 paper, 2020). "The addition of progenitor cells from the pSHF to the venous pole is also impaired in Hoxa1-/-; Hoxb1-/- hearts, resulting in abnormal development of the DMP and consequent atrioventricular septal defects (AVSDs)." (PMID 32804075, 2020).
autism (1 paper, 2010). Persistent deficits in social interaction and communication and interaction as well as a markedly restricted repertoire of activity and interest as well as repetitive patterns of behavior. "Collectively, our results do not support an association of large/moderate effect size between autism and HOXB1 gene variants marked by SNPs rs72338773 and rs12939811." (PMID 20678259, 2010). "A gene × gene interaction between HOXB1 and HOXA1 gene variants was initially proposed to contribute to autism." (PMID 20678259, 2010). "HOXB1 mutations do not represent a common cause of autism, nor do HOXB1 common variants play important roles in autism vulnerability." (PMID 20678259, 2010). "HOXB1 gene expression occurs very early in mouse development (E8.5-E9.5), at a time, interestingly, overlapping with the window of maximal prenatal sensitivity in rodent models of autism." (PMID 20678259, 2010). "An initial report, suggesting that HOXB1 could confer autism vulnerability in interaction with HOXA1, was not confirmed by five small association studies." (PMID 20678259, 2010).
Bell's palsy (1 paper, 2015). Partial or complete paralysis of the facial muscles of one side of a person's face. "Disruption of Hoxb1 function has been shown to result in facial nerve defects in mice, where the phenotype is similar to that of human patients with Bell’s Palsy or Moebius Syndrome." (PMID 26156498, 2015).
deafness (1 paper, 2023). An inherited or acquired condition characterized by the complete loss of the ability to hear from one or both ears. "Although this defect could be reproduced in a genetically modified mouse model in which the mouse Hoxb1 gene was constitutively inactivated, the cellular origin underlying HOXB1-related deafness was still unknown." (PMID 37738262, 2023). "By combining electrophysiological, anatomical, and molecular analyses, we show that Hoxb1-related deafness is partially reproduced only when motor neurons are severely reduced or lost during development and prior to hearing onset." (PMID 37738262, 2023).
endometriosis (1 paper, 2022). The growth of functional endometrial tissue in anatomic sites outside the uterine body. "Our results showed that HOXB1, AEBP1, and RORB were involved in endometriosis and SLE." (PMID 36532015, 2022).
erythroleukemia (1 paper, 2013). Acute erythroid leukemia characterised by the presence of at least 50% erythroid precursors and at least 20% myeloblasts in the bone marrow. "Among the AMLs the exceptions, showing HOXB1 expression, were the M6 staged erythroleukemias and the K562 cell line, possibly in agreement with their predominant erythroblastic cells component." (PMID 24148231, 2013).
Hearing impairment (1 paper, 2023). A decreased magnitude of the sensory perception of sound. "Moreover, recessive mutations in the human HOXB1 gene cause hereditary congenital facial paresis and sensorineural hearing impairments, suggesting an evolutionarily conserved key role for Hoxb1/HOXB1 in setting up functional auditory circuits." (PMID 37738262, 2023).
keratoconus (1 paper, 2021). A degenerative, structural disorder of the eye, characterized by a cone-shaped protrusion of the cornea. "We found evidence that SNPs associated with keratoconus often alter methylation of many genes, including LOX, PDDC1, SMAD3, HOXB1, KLF5, and BANP." (PMID 33649486, 2021).
non-small cell lung carcinoma (1 paper, 2013). A group of at least three distinct histological types of lung cancer, including non-small cell squamous cell carcinoma, adenocarcinoma, and large cell carcinoma.
renal cell carcinoma (1 paper, 2021). "We discovered that the mRNA levels of HOXB1/6/8/9 were significantly downregulated in renal cell carcinoma, while HOXB3/4/7 were upregulated in almost all tumors, including RCC." (PMID 34306077, 2021). "In this study, we analyzed the mRNA levels of HOXBs in tumors and normal tissue and found that the mRNA levels of HOXB1/6/8/9 are significantly downregulated in renal cell carcinoma, while those of HOXB3/4/7 are upregulated in nearly all the tumors, including renal cell carcinoma." (PMID 34306077, 2021).
viral infection (1 paper, 2024). "The expression of RA-regulated genes, such as RARA, RARB, CRABP1, HOXB1, and STRA6, were all downregulated after HSV-1 infection, thus further demonstrating that RA synthesis was inhibited by viral infection." (PMID 38989466, 2024).
tumor (13 papers, 2013 to 2025). "HOXB1 is reported to be differentially expressed in abnormal development and malignancy, indicating that the altered expression of HOXB1 is important in both oncogenesis and tumor suppression." (PMID 26565624, 2015). "The neoplasm metastasis associated genes KRT20, tumor protein D52 (TPD52), MUC1, and KIT are upregulated in the poor prognosis tumors while homeobox B1 (HOXB1) is downregulated." (PMID 24634783, 2014). "We propose HOXB1 as an additional member of the HOX family with tumour suppressor properties suggesting a HOXB1/ATRA combination as a possible future therapeutic strategy in AML." (PMID 24148231, 2013). "In this study we propose HOXB1 as an additional member of the HOX family with tumor suppressor properties." (PMID 24148231, 2013). "Accordingly, gene expression analysis showed the HOXB1-dependent down-regulation of some tumor promoting genes, paralleled by the up-regulation of apoptosis- and differentiation-related genes, thus supporting a tumor suppressor role for HOXB1 in AML." (PMID 24148231, 2013). "Increasing studies revealed that HOXB1 served as a significant tumor suppressor in several cancers." (PMID 34488545, 2021). "Previous studies indicated that HOXB1 was a significant tumor suppressor gene in many cancers." (PMID 34488545, 2021). "HOXB1 also reduces cell growth and proliferation and induces apoptosis and cell differentiation in acute myeloid leukemia, depending on the downregulation of some tumor-promoting genes, in parallel with the upregulated expression of apoptosis- and differentiation-related genes." (PMID 26565624, 2015). "The transcript levels of HOXB1, HOXA7, HOXB5, HOXD8, HOXB9, HOXA9, and HOXA11 were significantly lower in ccRCC tumor tissues compared to adjacent normal tissues, which was consistent in both TCGA and ICGC cohorts." (PMID 36387262, 2022). "However, other genes, such as HOXB1, HOXC5, HOXC12, HOXD3, and HOXD12, have extremely low expression levels, suggesting that they are more expressed in normal tissue samples than in tumor samples." (PMID 39980564, 2025). "Compared with the normal tissues, most of the HOX genes showed increased expression in tumor tissues, only HOXB1 and HOXD1 decreased expression in PGs samples, and the difference in expression of these HFGs in normal and tumor tissues was statistically significant except HOXB8 and HOXC12." (PMID 37547473, 2023).
cancer (11 papers, 2013 to 2023). A tumor composed of atypical neoplastic, often pleomorphic cells that invade other tissues. "While the KEGG analysis of all HOXB1 peaks shows enrichment for neurogenesis, neuronal processes, and behavior, there is some representation for genes associated with metabolism, biosynthesis, and cancer." (PMID 33546292, 2021). "Several studies have indicated that a member of HOX1 family: HOXB1 play critical role in the development of cancer." (PMID 35254502, 2022). "Considering that HOXB1 acted as a anti-oncogene in many cancers, we tried to confirm the roles of HOXB1 in CRC." (PMID 34488545, 2021). "Increasing studies have found that HOXB1 participated in regulating nuclear factor kappa B subunit 1(NF-kB) pathway, cancer cell proliferation and apoptosis." (PMID 34488545, 2021). "Meanwhile, RT-qPCR also found that the expression level of HOXB1 was less in cancer tissues than that in paracancerous." (PMID 34488545, 2021). "Genes such as TPD52, HOXB1, and KIF3A have been implicated in other cancer types and are connected with MCC-associated signaling." (PMID 24634783, 2014). "Finally, trying to dissect the molecular pathways possibly triggered by HOXB1, we searched its downstream genes by using an Atlas Human Cancer macroarray." (PMID 24148231, 2013). "Regardless of the important roles of HOXB1 in other cancers, the possible functions of HOXB1 in CRC remained to be unclear." (PMID 34488545, 2021). "In order to gain insight in the molecular mechanisms underlying HOXB1 effects in the leukemic phenotype, we investigated genes differentially expressed in HOXB1-negative vs HOXB1-positive HL60 cells by probing an Atlas Human Cancer cDNA macroarray." (PMID 24148231, 2013).
HOXB1 also shares sentences with these, for which no sentence is quoted: 22q11.2 deletion syndrome (1 paper); colorectal cancer (1); Facial palsy (1); hearing loss (1); hemolytic-uremic syndrome (1); hypogonadotropic hypogonadism (1); juvenile dermatomyositis (1); malignant glioma (1); microtia (1); Moebius syndrome (1); pituitary adenoma (1); renal clear cell carcinoma (1); systemic lupus erythematosus (1).